PEAK1 (pseudopodium enriched atypical kinase 1)
Diseases named in the same sentence as PEAK1 in open-access papers (continued):
Sharing a sentence is not in itself a finding about the gene and the disease.
tumor (28 papers, 2010 to 2025). "PEAK1 overexpression was associated with tumor size, tumor grade, tumor stage, advanced nodal status, regional recurrence, HER2, Ki-67 and chemotherapy status." (PMID 34554318, 2022). "First, authors have reported downregulation of PEAK1 and significant association between its downregulation and larger tumor diameter, poor differentiation, high probability of metastasis, and advanced stage." (PMID 34479583, 2021). "Our findings reveal PEAK1’s critical role in maintaining tight junction integrity and resistance to intestinal inflammation, extending its known function from promoting tumor cell proliferation and migration to essential physiological processes." (PMID 40707483, 2025). "Whereas PEAK1 K140Q was present within a subclone representing 24% of tumor cells (CCF = 0.24, s = 1), LRP5 A65V was estimated to be present in only 2% of cells in the primary tumor (CCF = 0.02, s = 1)." (PMID 38321573, 2024). "PEAK1 shRNA-transfected MCF-7 cells caused fewer tumor nodes, while Lv-PEAK1-transfected MCF-7 cells resulted in more tumor nodes." (PMID 34554318, 2022). "High PEAK1 expression was correlated with tumor size, high tumor grade, tumor stage, lymph node metastasis, recurrence, Ki-67 expression, Her-2 expression and chemotherapy resistance." (PMID 34554318, 2022). "Enhanced PEAK1 expression facilitates tumor cell survival, invasion, metastasis and chemoresistance." (PMID 34554318, 2022). "The results showed that PEAK1 was overexpressed in the SKMEL-19 tumor, and PEAK1 was downexpressed in the SKMEL-28 tumor." (PMID 34365903, 2021). "As before with the parental C3H10T1/2 MSCs, xenografting the shScr MSCs with the BT474 cells significantly increased primary tumor mass – an effect that was abrogated by PEAK1 knockdown using two unique shRNA constructs." (PMID 34239043, 2021). "In vivo, enforced PEAK1 expression promoted growth of subcutaneous tumor cells, and targeting PEAK1 expression suppressed growth of subcutaneous tumor cells." (PMID 34365903, 2021). "By evaluating PEAK1 expression across non-tumor cell types (i.e., 3 fibroblast-like, 1 endothelial and 1 innate immune cell lines), we further established that PEAK1 expression was highest within fibroblast-like cell types." (PMID 34239043, 2021). "While the specific cellular processes and/or molecular machinery governing these effects will require further characterization, one possibility is that stromal expression of PEAK1 enhances tumor vascularization." (PMID 34239043, 2021). "Yet, the connection of AXL to PEAK1 was completely dispensable for rescuing tumor growth, demonstrating the importance of AXL/PEAK1 specifically in the invasion process." (PMID 32681075, 2020). "Collectively, these data suggest that PEAK1 is required for both tumor growth and metastasis in a TNBC cellular model." (PMID 32681075, 2020). "Functionally, silencing PEAK1 inhibits cell proliferation, migration, and invasion in vitro and inhibits the growth of tumor xenografts in nude mice." (PMID 29449544, 2018). "Strikingly, VEGFA-induced tumor growth and microvascular density in Peak1−/− mice was significantly impaired compared to Peak1+/+ mice." (PMID 29872538, 2018). "It has been reported that PEAK1 drives cell migration and tumor metastasis in PDAC and breast cancer." (PMID 30038287, 2018). "We also found that PEAK1 was exclusively localized to the membrane of CRC cells, indicating that spatiotemporal regulation of PEAK1 was disrupted in tumor tissues." (PMID 29449544, 2018). "These in vivo results combined with the in vitro data reveal that PEAK1 promotes tumor metastasis and EMT." (PMID 30038287, 2018). "To investigate the role of PEAK1 in tumor growth in vivo, we used pLenti-shPEAK1 to stably knockdown endogenous PEAK1 expression in CRC cell." (PMID 29449544, 2018).
tumor (continued). "While PEAK1 is upregulated in both genetic backgrounds within PDAC cells under physiologically relevant tumor microenvironment conditions (i.e., the orthotopic site in nude mice), MST1R is only upregulated in KRas mutant cells implanted at this site." (PMID 27602776, 2017). "We found that increased levels of PEAK1 expression correlate with multiple markers of poor patient prognosis, such as metastatic lesions, disease relapse, advanced N stage, tumor grade, HER2 status, and stromal-derived prognostic predictor (SDPP) status." (PMID 26267863, 2015). "We also showed PEAK1 functions downstream of KRas to promote tumor growth, metastasis and therapy resistance using preclinical in vivo models of human tumor progression." (PMID 26267863, 2015). "In summary, PEAK1 mediates the switch in TGFβ signaling from tumor suppressor to tumor promoter in the context of extracellular fibronectin." (PMID 26267863, 2015). "We have recently demonstrated that PEAK1 promotes proliferation, migration and anchorage-independent growth in vitro and tumor formation in vivo." (PMID 21301050, 2010). "While it is clear now that PEAK1 has intrinsic tyrosine kinase activity in vitro, future studies should probe the role of its kinase domain during tumor progression and identify potential substrates of this novel cytoskeleton-associated kinase." (PMID 21301050, 2010). "To determine whether the effect of PEAK1 on in vitro chemosensitivity also is relevant to in vivo tumor growth, we injected female BALB/c mice with 5 × 105 MCF-7DOX or MCF-7 cells and evaluated the response to doxorubicin treatment." (PMID 34554318, 2022). "Furthermore, enforced PEAK1 expression promoted tumor growth and metastasis and EMT in vivo, and vice versa in vitro." (PMID 34365903, 2021). "To determine whether the AXL/PEAK1 connection is required for tumor growth and metastasis, we used the PEAK13PA mutant that we demonstrated to be uncoupled from AXL-induced phosphorylation." (PMID 32681075, 2020). "Developing strategies to interfere with pseudo-kinases, such as PEAK1, by pharmacologically targeting their bound kinases may prove useful to block tumor growth and metastasis." (PMID 32681075, 2020). "To clarify whether there might be a positive correlation between PEAK1 and tumor metastasis, we compared the results with the clinicopathological characteristics of the patients." (PMID 30038287, 2018). "Meanwhile, ectopic expression of PEAK1 promoted tumor metastasis and EMT in vivo." (PMID 30038287, 2018). "We further found that PEAK1 significantly promoted tumor metastasis and EMT in a mouse model." (PMID 30038287, 2018). "Indeed, E0771 tumors expressing VEGFA showed significantly increased microvascular density and tumor size in Peak1+/+ animals, compared to tumors derived from control E0771 cells or E0771 cells expressing GFP only." (PMID 29872538, 2018). "Also, increased SRC-dependent PEAK1 expression by blockade of ERBB2 expression activates tumour growth." (PMID 28871116, 2017). "Thus, we sought to evaluate the role of PEAK1 in the switching of TGFβ from a tumor suppressing to tumor promoting factor." (PMID 26267863, 2015). "Notably, we discovered that high PEAK1 expression causes TGFβ to lose its anti-proliferative effects, and potentiates TGFβ-induced proliferation, EMT, cell migration and tumor metastasis in a fibronectin-dependent fashion." (PMID 26267863, 2015).
tumor (continued). "Although we are the first to clone and directly study the function of PEAK1, several independent lines of evidence also suggest that PEAK1 and its only family member sgk223 (pragmin) (33% overall homology to PEAK1) play integral roles in regulating cell motility and tumor progression." (PMID 21301050, 2010). "For example, an LRP5 activating mutation and a PEAK1 mutation originally found solely in a metastasis were subsequently detected within the primary tumor by UDS-UMI/UDG and estimated to be present within the same rare subclone comprised of only 2% of tumor cells." (PMID 38321573, 2024). "Therefore, it was hypothesized that CDC5L might bind to the PEAK1 promoter to regulate PEAK1 expression and further activate downstream signaling pathways to synergistically play a tumor‐promoting role." (PMID 32167655, 2020). "Thus, PEAK1 is highly expressed in ECs of tumor-associated vessels, but not in CD31-positive ECs present in adjacent normal breast tissues." (PMID 29872538, 2018). "Thus, identifying tumor subtypes in which PEAK1 levels or PEAK1-induced EMT gene signatures are elevated may facilitate the selection of patients that will respond positively to anti-TGFβ treatment regimens." (PMID 26267863, 2015). "Unsurprisingly, decreased cell and tumor growth was observed in MCF-7 cells with suppressed PEAK1 expression, whereas cell growth was increased in MCF-7 cells overexpressing PEAK1 in vitro and in vivo." (PMID 34554318, 2022). "This revealed that the stromal co-expression of PEAK1 and SNAI2 was significantly increased in HER2-positive tumor tissues (n = 79)." (PMID 34239043, 2021). "However, the exact mechanism of PEAK1 action in tumor metastasis and EMT remains unclear." (PMID 30038287, 2018). "Genetic knockdown of eIF5A inhibited PDAC cell growth in vitro and orthotopic tumor formation in vivo, potentially through pseudopodium-enriched atypical kinase 1 (PEAK1), which is essential to PDAC tumor growth, metastasis, and gemcitabine resistance." (PMID 28083147, 2016). "The ancestral primary tumor subclone responsible for seeding the metastasis was identified in 29% of patients, implicating several putative drivers in metastatic seeding including LRP5 A65V and PEAK1 K140Q." (PMID 38321573, 2024). "In addition, PEAK1 mediates TGF-β signaling and controls extracellular microenvironment in tumor cells." (PMID 34365903, 2021). "Collectively, these results demonstrate that the AXL/PEAK1 signaling complex is essential for the cell migration/invasion and FA turnover that lead to metastasis, yet this complex is not required for tumor growth." (PMID 32681075, 2020). "Hence, miR-181d is an important tumor suppressor miRNA in CRC invasion and metastasis, and PEAK1 is downstream effector of miR-181d in its target network." (PMID 29449544, 2018). "PEAK1 overexpression did not correlate with age, tumor size, histology, tumor differentiation or TNM stage (P > 0.05), but was significantly associated with gender and LN metastasis (P < 0.05)." (PMID 30038287, 2018). "On the contrary, PEAK1 knockout had the opposite effects on tumor metastasis and EMT in vivo (data not shown)." (PMID 30038287, 2018). "Notably, this switching of TGFβ to a pro-proliferative factor in the presence of high PEAK1 levels correlates with PEAK1’s ability to promote TGFβ-induced motility, EMT gene expression, mesenchymal cell morphology and tumor metastasis." (PMID 26267863, 2015). "PEAK1 silencing and/or TGFβ treatment in the CA1h cells grown on fribronectin prior to xenografting did not affect tumor growth on the CAM." (PMID 26267863, 2015). "Recently, PEAK1 (a novel non-receptor tyrosine kinase), highly expressed in invasive breast cancer, has been described as relevant for switching TGF-β from a tumor suppressor to a tumor-promoting factor." (PMID 28067804, 2017). "Uncoupling of PEAK1 from AXL signaling decreases metastasis in vivo, but not tumor growth." (PMID 32681075, 2020).
PEAK1 also shares sentences with these, for which no sentence is quoted: autism (1 paper); breast adenocarcinoma (1); cardiomyopathies (1); chronic kidney disease (1); Hashimoto thyroiditis (1); inflammation (1); metastatic disease (1); nodular goiter (1); Papillary Thyroid Cancer (1); rectal cancer (1); schizophrenia (1); small cell lung carcinoma (1); subacute thyroiditis (1); ulcerative colitis (1).